ATP9B (ATPase phospholipid transporting 9B)
Synonyms: ATPIIB; NEO1L; HUSSY-20; ATPASEP; hMMR1
Tractability: Antibody: UniProt predicts a signal peptide or a membrane-spanning region; its Gene Ontology location is reachable by antibodies, with medium confidence. PROTAC: ubiquitination databases record sites on it; its protein half-life has been measured.
Gene: Protein-coding gene on chromosome 18 (79,069,272 to 79,378,391, forward strand). Ensembl gene ENSG00000166377.
Subcellular location: Golgi apparatus, trans-Golgi network membrane
Pathways (Reactome):
Transport of small molecules: Ion transport by P-type ATPases
Gene Ontology:
Molecular function: ATP binding; ATP hydrolysis activity; ATPase-coupled intramembrane lipid transporter activity; magnesium ion binding; nucleotide binding
Biological process: endocytosis; phospholipid translocation; retrograde vesicle-mediated transport, Golgi to endoplasmic reticulum; phospholipid transport
Cellular component: perinuclear region of cytoplasm; trans-Golgi network; endosome; cytoplasm; endomembrane system; Golgi apparatus; membrane
Genetic constraint (gnomAD): Loss-of-function variants: 80 observed, 112.45 expected, observed/expected ratio (o/e) 0.71, 90% interval 0.59 to 0.86. The upper end of that interval is the gene's LOEUF score, 0.86, which puts it in group 3 of 6, group 1 being the genes least tolerant of losing a copy. Missense variants: 1,192 observed, 1,252 expected, observed/expected ratio (o/e) 0.95, 90% interval 0.91 to 1. Synonymous variants: 513 observed, 488.44 expected, observed/expected ratio (o/e) 1.05, 90% interval 0.98 to 1.13.
Homologues: Orthologues: chimpanzee ATP9B (99% identical), macaque ATP9B (99% identical), guinea pig ATP9B (94% identical), pig ATP9B (93% identical), rat Atp9b (93% identical), mouse Atp9b (92% identical), dog ATP9B (90% identical), tropical clawed frog atp9b (88% identical), rabbit ATP9B (87% identical), zebrafish atp9b (84% identical), Drosophila melanogaster CG31729 (61% identical), Caenorhabditis elegans tat-5 (54% identical), and 1 more. Paralogues in human: ATP9A (69% identical), ATP8B2 (29% identical), ATP8B1 (29% identical), ATP8B4 (28% identical), ATP10B (28% identical), ATP11B (27% identical), ATP10D (27% identical), ATP10A (27% identical), ATP11A (27% identical), ATP8A2 (27% identical), ATP8A1 (26% identical), ATP11C (25% identical), and 1 more.
Diseases named in the same sentence as ATP9B in open-access papers:
ATP9B is named in the same sentence as 7 diseases in open-access papers, as found by Europe PMC text mining. Sharing a sentence is not in itself a finding about the gene and the disease. The quoted sentences say what the papers report.
osteoarthritis (4 papers, 2018 to 2025). A noninflammatory degenerative joint disease occurring chiefly in older persons, characterized by degeneration of the articular cartilage, hypertrophy of bone at the margins and changes in the synovial membrane. "Specifically, ZNF25 was suggested as a candidate gene for osteoblast differentiation in humans, KLHL14 as a candidate gene for bone strength in chicken, and ATP9B as a candidate gene regulating the progression of osteoarthritis." (PMID 40965274, 2025). "Recent studies have shown that circRNAs, such as circular RNA Atp9b and circRNA hsa_circ_0005105, are involved in osteoarthritis." (PMID 32626759, 2020).
anxiety disorder (1 paper, 2024). A category of psychiatric disorders which are characterized by anxious feelings or fear often accompanied by physical symptoms associated with anxiety. "Genes related to metal binding or metal ion binding (e.g., ATP9B, LMAN2L, TNS3, and TSHZ2) may play a role in the development of anxiety disorders." (PMID 39165506, 2024).
gliosarcoma (1 paper, 2019). A rare histological variant of glioblastoma (WHO grade IV) characterized by a biphasic tissue pattern with alternating areas displaying glial and mesenchymal differentiation (WHO). "Several mRNAs: MLYCD, CFAP54, ATP9B, and TMEM212 were significantly downregulated in gliosarcomas when compared to GBMs." (PMID 30818875, 2019).
cancer (2 papers, 2017 to 2019). A tumor composed of atypical neoplastic, often pleomorphic cells that invade other tissues. "In addition, we found that knockdown of EGFR and CLPTM1L expression significantly inhibited migration and invasion, whereas knockdown of ATP9B or PQLC1 significantly enhanced migration and invasion of cancer cells." (PMID 28548104, 2017). "Moreover, we found that knockdown of expression of CLPTM1L, ATP9B, PQLC1 as well as EGFR significantly inhibited cancer cell migration and invasion." (PMID 28548104, 2017).
ATP9B also shares sentences with these, for which no sentence is quoted: glioma (1 paper); ovarian carcinoma (1); tumor (1).